PEX14 (peroxisomal biogenesis factor 14)
Description:
Component of the PEX13-PEX14 docking complex, a translocon channel that specifically mediates the import of peroxisomal cargo proteins bound to PEX5 receptor. The PEX13-PEX14 docking complex forms a large import pore which can be opened to a diameter of about 9 nm (By similarity). Mechanistically, PEX5 receptor along with cargo proteins associates with the PEX14 subunit of the PEX13-PEX14 docking complex in the cytosol, leading to the insertion of the receptor into the organelle membrane with the concomitant translocation of the cargo into the peroxisome matrix. Plays a key role for peroxisome movement through a direct interaction with tubulin.
Synonyms: NAPP2; PBD13A; Pex14p; dJ734G22.2
Tractability: Antibody: UniProt predicts a signal peptide or a membrane-spanning region. PROTAC: ubiquitination databases record sites on it; its protein half-life has been measured; a small molecule that binds it is known.
Gene: Protein-coding gene on chromosome 1 (10,472,288 to 10,630,758, forward strand). Ensembl gene ENSG00000142655.
Subcellular location: Peroxisome membrane
Subcellular location (Human Protein Atlas): Peroxisomes; Nucleoli fibrillar center
Pathways (Reactome):
Protein localization: Class I peroxisomal membrane protein import; Peroxisomal protein import
Metabolism of proteins: E3 ubiquitin ligases ubiquitinate target proteins
Gene Ontology:
Molecular function: beta-tubulin binding; identical protein binding; microtubule binding; protein binding; protein transmembrane transporter activity; protein-macromolecule adaptor activity; signaling receptor binding
Biological process: cellular response to reactive oxygen species; microtubule anchoring; negative regulation of DNA-templated transcription; peroxisome transport along microtubule; protein import into peroxisome matrix; protein import into peroxisome matrix, docking; protein import into peroxisome matrix, substrate release; protein import into peroxisome matrix, translocation; protein-containing complex assembly; peroxisome organization
Cellular component: membrane; peroxisomal importomer complex; peroxisomal membrane; peroxisome; protein-containing complex; cytosol; nucleus
Genetic constraint (gnomAD): Loss-of-function variants: 14 observed, 40.38 expected, observed/expected ratio (o/e) 0.35, 90% interval 0.23 to 0.54. The upper end of that interval is the gene's LOEUF score, 0.54, which puts it in group 2 of 6, group 1 being the genes least tolerant of losing a copy. Missense variants: 342 observed, 426.57 expected, observed/expected ratio (o/e) 0.8, 90% interval 0.73 to 0.88. Synonymous variants: 182 observed, 187.73 expected, observed/expected ratio (o/e) 0.97, 90% interval 0.86 to 1.1.
Gene-disease validity (ClinGen):
ClinGen rates the evidence that PEX14 causes each of these diseases.
peroxisome biogenesis disorder (autosomal recessive): Definitive.
Homologues: Orthologues: chimpanzee PEX14 (100% identical), macaque PEX14 (100% identical), pig PEX14 (94% identical), dog PEX14 (93% identical), rat Pex14 (93% identical), mouse Pex14 (92% identical), guinea pig PEX14 (90% identical), rabbit PEX14 (88% identical), tropical clawed frog pex14 (68% identical), zebrafish pex14 (63% identical), Drosophila melanogaster Pex14 (21% identical), Caenorhabditis elegans prx-14 (18% identical).
Diseases named in the same sentence as PEX14 in open-access papers:
PEX14 is named in the same sentence as 29 diseases in open-access papers, as found by Europe PMC text mining. Sharing a sentence is not in itself a finding about the gene and the disease. The quoted sentences say what the papers report.
Zellweger syndrome (4 papers, 2019 to 2026). "Mutations in PEX14 have been found in a few patients with Zellweger syndrome and peroxisome biogenesis deficiency." (PMID 40632619, 2026). "Pex14 mutation can cause Zellweger syndrome, which is clinically manifested by hyperbilirubinemia, hypoketotic dicarboxylic aciduria, and low plasmalogen concentration." (PMID 31781323, 2019). "Zellweger spectrum disorders (ZSDs), including archetypal Zellweger syndrome, neonatal adrenoleukodystrophy (NALD) and infantile Refsum disease (IRD), are PBDs caused by mutations in peroxin genes (PEX1, PEX2, PEX3, PEX5, PEX6, PEX10, PEX11β, PEX12, PEX13, PEX14, PEX16, PEX19 or PEX26)." (PMID 40949164, 2025).
breast carcinoma (3 papers, 2015 to 2023). "In ER-negative subtype, PEX14 (OR = 1.645, p < 0.001) stood out as the sole protein, even showing a stronger causal effect compared to breast cancer." (PMID 38304232, 2023). "Our research reveals a significant causal risk association of PEX14 with breast cancer (OR = 1.201), particularly in ER-negative subtype (OR = 1.645)." (PMID 38304232, 2023). "This further underscores PEX14’s pivotal role in managing oxidative stress and cell viability, marking its significance in breast cancer research." (PMID 38304232, 2023). "Overall, we found 5 proteins (PEX14, CTSF, SNUPN, CSK, PARK7) with strong causal links to breast cancer." (PMID 38304232, 2023). "Specifically, PEX14 (OR = 1.201, p = 0.016) and CTSF (OR = 1.114, p < 0.001) both displayed positive and causal association with breast cancer." (PMID 38304232, 2023). "Among the “Strong” Tiers, PEX14 (Z = 4.839) and CTSF (Z = 3.681) had a positive association with breast cancer." (PMID 38304232, 2023). "Notably, PEX14 not only showed the same trend as observed in breast cancer (Z = 4.839, p = 0.0004) but also exhibited a notably stronger effect (Z = 5.929, p = 2.02E-6)." (PMID 38304232, 2023). "We note that at the PEX14 locus, the overlap with the posterior probability for breast cancer was higher for transcript uc001arm than for exon 7, hinting at the possibility that it is this entire transcript rather than simply exon 7 that is implicated in breast cancer risk." (PMID 26472073, 2015).
allergic disease (1 paper, 2017). An immune response that occurs following re-exposure to an innocuous antigen, and that requires the presence of existing antibodies against that antigen. "Some of these genes have a known function that is relevant to allergic disease, including F11R, CD247, PGAP3, AAGAB, CAMK4 and PEX14, and so could be prioritized for functional follow-up." (PMID 29333270, 2017).
attention deficit-hyperactivity disorder (1 paper, 2025). A disorder characterized by a marked pattern of inattention and/or hyperactivity-impulsivity that is inconsistent with developmental level and clearly interferes with functioning in at least two settings (e.g. at home and at school). "These include regions with nearest protein-coding genes such as BCAS3, RFX3, SOBP, and PEX14, mutations in which have been linked to intellectual disability, neurological deficits, attention deficit hyperactivity disorder, or autism spectrum disorders." (PMID 41279093, 2025).
cardiac arrhythmia (1 paper, 2020). Any disturbances of the normal rhythmic beating of the heart or MYOCARDIAL CONTRACTION. "On the other hand, KD of the key factors (peroxines) involved in peroxisomal import process (Pex5, Pex1, and Pex14) in oenocytes significantly induced cardiac arrhythmia." (PMID 32523050, 2020).
COVID-19 (1 paper, 2025). A disease caused by infection with severe acute respiratory syndrome coronavirus 2. "Suppressed PEX3, PMP70 and PEX14 immunolabeling in vitro.Suppressed PEX3, PEX11β, PEX5L and PEX14 mRNA levels and decreased PMP70 and PEX14 protein levels in brain tissue from COVID-19 patients versus controls.Suppressed Pex3 mRNA and catalase protein in brains from infected hamsters." (PMID 40949164, 2025).
dysplasia (1 paper, 2021). A usually neoplastic transformation of the cell, associated with altered architectural tissue patterns. "Nevertheless, the present results suggest that downregulation of Pex14 underlies, at least in part, the pancreatic dysplasia in the IUGR fetus." (PMID 34471469, 2021).
Hepatic steatosis (1 paper, 2024). Steatosis is a term used to denote lipid accumulation within hepatocytes. "IF staining of PEX14, the peroxisomal biogenesis marker, further confirmed no obvious alteration (P > 0.05) of peroxisome level in U‐NHPs, implying the limited participation of peroxisome in undernutrition‐related hepatic steatosis." (PMID 38816931, 2024).
hepatoma (1 paper, 2020). "Similar phosphorylation profile of Pex14 was observed in rat hepatoma Fao cells under normal culture condition." (PMID 32831175, 2020).
intrauterine growth restriction (1 paper, 2021). "We previously reported that Pex14, a peroxin protein involved in the biogenesis and degradation of peroxisomes, is markedly reduced in the pancreas of an intrauterine growth restriction fetus and last into adulthood." (PMID 34471469, 2021).
laryngeal carcinoma (1 paper, 2021). Carcinoma that arises from the laryngeal epithelium. "This suggests that EGFR and INHBA can serve as prognostic hub genes for laryngeal cancer collectively with pRS genes (CFLAR, DAPK2, TSC2, CAPN10, MBTPS2, PEX14, FADD and ST13)." (PMID 34093817, 2021).
neuroblastoma (1 paper, 2021). Neuroblastoma (NB) is the most common solid, extracranial childhood tumor. "In neuroblastoma, PEX14 down-regulation was found to be associated with tumor progression and poor prognosis." (PMID 34093817, 2021).
Peroxisomal Biogenesis Disorder (1 paper, 2017). "Mutations in PEX14 (Peroxisomal Biogenesis Factor 14) (intronic lead variant rs6687430) underlie certain forms of Zellweger Spectrum Peroxisomal Biogenesis Disorder (MIM: 614887), a syndrome characterized by absence of functional peroxisomes and systemic neurological impairment." (PMID 29313844, 2017).
renal tumour (1 paper, 2018). "We collected 10 renal tumour samples with characteristic eosinophilic cytoplasmic inclusions (ECIs) and found that the ECIs were majorly composed of sequestosome 1/P62, neighbor of BRCA1 gene 1 (NBR1), PEX14, and CATALASE1 (CAT1)." (PMID 29967346, 2018).
sickle cell disease (1 paper, 2024). Sickle cell anemias are chronic hemolytic diseases that may induce three types of acute accidents: severe anemia, severe bacterial infections, and ischemic vasoocclusive accidents (VOA) caused by sickle-shaped red blood cells obstructing small blood vessels and capillaries. "CD163 prevented hepatobiliary injury in sickle cell disease by means of inhibiting oxidative stress, inflammation, and thrombosis; and the reducing PEX14 impaired peroxisomes and caused liver oxidative stress." (PMID 39598613, 2024).
triple-negative breast carcinoma (1 paper, 2023). An invasive breast carcinoma which is negative for expression of estrogen receptor (ER), progesterone receptor (PR), and human epidermal growth factor receptor 2 (HER2). "Notably, PEX14 has been identified as a key risk factor in triple-negative breast cancer (TNBC) and is one of the top five genes influencing adaptive anti-tumor immunity, as shown in a TNBC model study using a whole-genome RNAi screening platform." (PMID 38304232, 2023).
tumor (6 papers, 2005 to 2023). "Real time-PCR studies of all the genes in the region on cDNA-samples showed a significant reduction of mRNA levels in high stage NB tumours compared to low stage tumour mRNA levels, ranging from 49% for PEX14 to 79% for APITD1." (PMID 15740626, 2005). "Notably, 8 autophagy-related genes (CAPN10, DAPK2, MBTPS2, ST13, CFLAR, FADD, PEX14 and TSC2) and 2 immune cells (Mast cells and Eosinophils) were revealed to be highly associated with tumor prognosis." (PMID 34093817, 2021). "Lower expression in cell lines was seen in KIF1B and equal levels of cell lines and stage 2 primary tumours in UBE4B, PGD and PEX14." (PMID 15740626, 2005). "Notably for FAT4, BFAR, CRB2, and PEX14, we did not identify somatic mutations in the wild-type allele of these genes in the cases carrying germline mutations, suggesting that if they are contributing to tumor formation, they most likely do not function as classical tumor suppressors." (PMID 31101826, 2019). "The analyzed fragments of the genes UBE4B, KIF1B, PGD, DFFA and PEX14 were not methylated in the panel of NB primary tumours and cell lines." (PMID 15740626, 2005). "The genes UBE4B, KIF1B, PGD, APITD1, DFFA and PEX14 are down-regulated in high stage NB tumours, a feature that can not be explained by CpG island methylation." (PMID 15740626, 2005). "Hence, the six genes UBE4B, KIF1B, PGD, APITD1, DFFA and PEX14 are down-regulated in high stage NB tumours, a feature that can not be explained by methylation, rather by a mechanism still remaining to be discovered." (PMID 15740626, 2005).
infection (4 papers, 2022 to 2025). The state of being infected such as from the introduction of a foreign agent such as serum, vaccine, antigenic substance or organism. "To investigate whether MoKat2 plays a role in the regulation of peroxisome dynamics in response to host-derived ROS during infection, we examined the peroxisome morphology in IH of Guy11, ∆Mokat2, and MoKAT2-C expressing Pex14-GFP at 24, 48, and 72 hpi with or without DPI treatment, respectively." (PMID 37966176, 2023). "Expression of peroxisome biogenesis-related transcripts such as PEX14, PEX5, and PEX11B were not altered after 6 and 12 h of STM infection." (PMID 39695325, 2025).
cancer (2 papers, 2023 to 2024). A tumor composed of atypical neoplastic, often pleomorphic cells that invade other tissues. "For the extracellularly releasing process, S100A11 is required to meet PEX14, a peroxisome membrane protein, leading to peroxisomal co-option, subsequent homodimerization, and secretion in cancer cells." (PMID 38842658, 2024).
PEX14 also shares sentences with these, for which no sentence is quoted: Breast Invasive Carcinoma (1 paper); glioma (1); infantile Refsum disease (1); Intellectual disability (1); neurodegenerative disease (1); osteoporosis (1); ovarian carcinoma (1); prostate carcinoma (1); Seckel syndrome (1); Zellweger Spectrum (1).